YY1 (YY1 transcription factor)
Diseases named in the same sentence as YY1 in open-access papers (continued):
Sharing a sentence is not in itself a finding about the gene and the disease.
melanoma (continued). "Interestingly, in the presence of TGF-β1, YY1 loss increased Smad2 phosphorylation, indicating that melanoma cells display enhanced sensitivity to TGF-β1 when YY1 levels are low." (PMID 35693944, 2022). "To investigate the role of YY1 in human melanoma cells, we performed siRNA-mediated YY1 knockdown experiments in three human melanoma cell lines with different mutational backgrounds, namely M010817 (NRASQ61K-mutated), Mel888 (BRAFV600E-mutated) and Skmel28 (BRAFV600E-mutated)." (PMID 35693944, 2022). "YY1 is essential for the generation of embryonic melanocytic lineage and adult melanocyte stem cells, and melanoma is strongly associated with the CSC phenotype; thus, YY1 could be regulating the melanoma CSC phenotype." (PMID 33728560, 2021). "Intriguingly, while some NCSC factors, such as SOX10 and YY1, are activated upon melanoma formation and are required for melanoma growth, other NCSC-associated factors, such as CD271/NGFR/p75NTR, PAX3, and FOXD3 promote melanoma cell invasiveness and metastasis formation." (PMID 34417458, 2021). "Similarly, functional assays demonstrated that mitochondrial bioenergetics, protein synthesis, and other metabolic pathways were compromised by the loss of YY1 expression in melanoma cells." (PMID 33728560, 2021). "Based on above statistic results that YY1 expression displayed close association with metastasis and malignant degree of tumor, we proposed that it might play an extremely important role in melanoma cell migration and invasion." (PMID 26104682, 2015). "Upon YY1 deletion it was found that both oxygen consumption and protein synthesis rate decreased showcasing its role in maintaining metabolic needs of melanoma cells." (PMID 41327312, 2025). "The researchers of this study suggest YY1 knockdown induces a “phenotype switching” where melanoma cells transition from a proliferative state to an invasive state." (PMID 41327312, 2025). "It has been found that in melanoma patients, inhibiting YY1 restores downstream Fas- and TRAIL-mediated apoptosis." (PMID 38539569, 2024). "The presence of PD-1-positive T cells and YY1 protein was correlated with disease progression in melanoma and immune resistance to ICIs in lung adenocarcinoma." (PMID 38339244, 2024). "Inhibition of YY1 through NO allows melanoma cells to be more responsive to immunotherapies including anti-PD-L1-dependent treatment, further allowing anti-PD-L1 therapy to attack the cancer." (PMID 38539569, 2024). "For example, in malignant melanoma, it was found that YY1 plays a critical role in apoptosis resistance, metastasis promotion, and the regulation of immune response." (PMID 38539569, 2024). "In melanoma, proper YY1 expression was found to be crucial for tumor initiation and formation in a transgenic melanoma mouse model." (PMID 35693944, 2022). "Previously, we conditionally ablated Yy1 in the melanocytic lineage of this model to reveal a crucial role of Yy1 in melanoma formation and growth." (PMID 35693944, 2022). "Still, many questions arise regarding the exact role of YY1 in melanoma pathogenesis, progression, and drug resistance." (PMID 35719931, 2022). "Bioinformatics analyses on the expression of YY1 in melanomas seem to confirm the relevant role of this transcription factor in melanoma development and progression." (PMID 35719931, 2022). "In the present review, we have highlighted the importance of the overexpression of the transcription factor YY1 in malignant melanoma tumorigenesis and its possible role in tumor surveillance and treatment resistance." (PMID 35719931, 2022). "In melanoma, NADPH oxidase 3 (NOX3) and RNA 2',3'-cyclic phosphate and 5'-OH ligase (RTCB) mutations reduce YY1 expression." (PMID 35791393, 2022). "At the same time, metabolic reprogramming by YY1 was shown to interfere with melanoma cell proliferation indicating that YY1 exerts its two functions in phenotype switching–promoting proliferation and suppressing invasion–via its role as metabolic regulator." (PMID 35693944, 2022).
melanoma (continued). "The highest expression of YY1 and Sox2 proteins represented the group assembled by melanoma, colorectal cancer, and lymphomas." (PMID 35719931, 2022). "MetacoreTM process network analysis for downregulated genes indicated that YY1 positively regulates genes involved in cell cycle regulation in agreement with the previously reported role of YY1 in melanoma cell proliferation." (PMID 35693944, 2022). "Similar to SALL4, YY1 is another transcription factor (TF) that promotes melanoma initiation and tumor growth while being averse to cancer invasiveness; indeed, mice conditionally depleted for Yy1 show an increase in metastasis formation." (PMID 36551603, 2022). "In melanoma, YY1 was identified to orchestrate metabolic pathways and protein synthesis crucial for cell survival and proliferation." (PMID 35693944, 2022). "In all three human melanoma cell lines tested, YY1 knockdown significantly promoted the migration capacity of the cells." (PMID 35693944, 2022). "Gene set enrichment analysis of YY1 knockdown melanoma cells revealed Signal Transduction_TGF-beta, GDF and Activin signaling, as one of the top upregulated pathways, which encompassed the genes TGFB1, TGFBRI and TGFBRII." (PMID 35693944, 2022). "Next, we quantified DCT-positive melanoma cells in both, the lungs of Yy1 knockout and control animals." (PMID 35693944, 2022). "YY1 plays a crucial role in metabolic reprogramming that converts a normal melanocyte into a melanoma-competent cell." (PMID 35719931, 2022). "The transcription factor YY1 is a master regulator of metabolism that we have previously shown to orchestrate a metabolic program required for melanoma formation." (PMID 35693944, 2022). "It is therefore conceivable that YY1 knockdown induces an invasiveness gene signature in melanoma cells by activation of a metabolic stress program." (PMID 35693944, 2022). "In this study, we demonstrate that YY1, while being essential for primary melanoma formation, suppresses metastatic spreading." (PMID 35693944, 2022). "Additional bioinformatics studies also suggested an association between YY1 and MITF in melanoma progression." (PMID 35719931, 2022). "Apparently, YY1 plays a key role in melanoma because its expression levels correlate with advanced tumor stages and ectopic YY1 downregulation inhibits the proliferation, migration, invasion, and resistance to anticancer therapies." (PMID 33728560, 2021). "It has been found that metabolic programming that accompanies transition from melanocytes to melanoma cells is, at least partially, dependent on YY1 expression and that YY1 knockdown is sufficient to prevent melanocyte transformation." (PMID 34638331, 2021). "RNA-seq and YY1 ChIP-Seq analyses were performed after RNAi-mediated knockdown of YY1 to extend these observations to human melanoma cells." (PMID 33728560, 2021). "siRNA knockdown of YY1 in the UACC903 melanoma cell line demonstrated a weak but consistent reduction of MX2 levels by four different sets of siRNAs (14–32% decrease, P = 1.5e−3–1.9e−5, one-sample Wilcoxon test) indicating a regulation of MX2 levels by YY1." (PMID 32483191, 2020). "To investigate the effects of EC-specific deletion of YY1 on tumor growth, we inoculated melanoma B16-F10 cells on the dorsal side of 8-week-old mice in both YY1i∆EC and WT mice." (PMID 33235311, 2020). "The expression of YY1 in melanoma ECs was further confirmed by immunofluorescence analysis using confocal microscopy." (PMID 33235311, 2020). "We subsequently performed chromatin immunoprecipitation (ChIP) using anti-YY1 antibody and scanned a ~5 Mb genomic region encompassing rs398206 in three melanoma cell lines representing each genotype of rs398206 (AA, AC, and CC)." (PMID 32483191, 2020). "For example, YY1 inhibits proliferation in pancreatic cancer through downregulation of SOX2, while in melanoma, YY1 promotes tumor growth, and YY1 cKO prevents tumorigenesis in a melanoma murine model." (PMID 33102493, 2020).
melanoma (continued). "In this report, YY1 has been shown to be essential for proliferation, survival and metastasis of melanoma cells." (PMID 31824839, 2019). "YY1 has been found to be overexpressed in melanoma compared to benign nevi and normal tissue control with positive correlation with metastasis and tumor stage." (PMID 31217904, 2019). "YY1 expression was shown to be elevated in melanoma patient samples and its expression levels were shown to increase as tumor progresses to advanced stages." (PMID 31824839, 2019). "Since melanocytes originate from NCSCs during development, these authors went on to show that conditional ablation of YY1 impairs melanoma tumor growth in a melanoma mouse model." (PMID 31824839, 2019). "In melanoma cells, YY1 activates the transcription of Snail through binding to the 3’ enhancer, suggesting its involvement in the epithelial-mesenchymal transition during cancer metastasis." (PMID 28827574, 2017). "When tiers three and four are grouped together, such that the results from liver, stomach, renal, pancreatic, urothelial cancers, lymphoma and melanoma are pooled, there is also a strong inverse correlation between YY1 and BMI1 expressions (R2 = −0.7)." (PMID 27225481, 2016). "In this study, we perform RT-qPCR analysis to detect the YY1 mRNA level in both benign nevi and melanoma specimens." (PMID 26104682, 2015). "Elevated YY1 levels were observed in patients with melanoma, compared with the levels detected in age/gender-matched controls with benign nevi and normal tissue controls." (PMID 26104682, 2015). "As expected, inhibition of YY1 increased miR-9 by ~2-fold, suggesting a transcriptional inhibition by YY1 on miR-9 in melanoma cells." (PMID 26104682, 2015). "Given the essential nature of YY1 function in different human carcinomas, we decided to investigate the role for YY1 in human melanoma." (PMID 26104682, 2015). "We further identified YY1-targeted miR-9, which was repressed in melanoma cells, was regulated by YY1 and elucidated its functional significance in regulating melanoma growth and progression." (PMID 26104682, 2015). "In that regard, it would be interesting to test the biological and mechanistic significance of YY1 in melanoma." (PMID 26104682, 2015). "Silencing of YY1 inhibited proliferation, cell cycle progression, migration and invasion in melanoma cells, while ectopic of miR-9 did the same." (PMID 26104682, 2015). "A significantly increased level of YY1 was seen in patients with melanoma (primary and metastatic melanomas), compared with the levels detected in age/gender-matched controls with benign nevi (p < 0.01) and normal tissue controls (p < 0.001)." (PMID 26104682, 2015). "Taken together, these results indicated that inhibition of YY1 can efficiently inhibited tumor cell proliferation and cell cycle in vitro, suggesting its oncogenic role in modulating tumorigenicity of melanoma cells." (PMID 26104682, 2015). "In line with the other studies, our results suggested YY1 as a transcriptional repressor of miR-9 and a promoter of melanoma growth and progression by modulating the miR-9 ~ RYBP axis." (PMID 26104682, 2015). "Elevated YY1 levels were observed in patients with melanoma, compared with benign nevi and normal tissue controls, and the increased YY1 was associated with melanoma metastasis state and tumor stage." (PMID 26104682, 2015). "Prolonged depletion of YY1 led to decreased cell numbers in both YY1 knockdown MALME-3M melanoma cells and human foreskin primary melanocytes (HFM), similar to MITF knockdown." (PMID 22570637, 2012). "Through gene expression analysis following YY1 knockdown in melanoma cell lines, the study found that YY1 positively regulates genes involved in cell cycle and proliferation, while repressing genes linked to cell adhesion, epithelial-to-mesenchymal transition (EMT), and TGF-β signaling." (PMID 41327312, 2025).
melanoma (continued). "Moreover, utilizing miRNAs to downregulate YY1 expression led to beneficial outcomes in melanoma patients due to the inhibition of the EMT." (PMID 38539569, 2024). "This pathway drives YY1 expression, leading to PD-1 upregulation and the persistence of melanoma." (PMID 39796650, 2024). "In a recent study, YY1 promoted cancer progression in human melanomas." (PMID 37686541, 2023). "Given that YY1 is essential for many biological processes, it may be an interesting prognostic target for melanoma." (PMID 35719931, 2022). "These authors also investigated whether YY1 mediated autophagy could modulate the activity of one of the commonly used in melanoma patients BRAF inhibitors – vemurafenib." (PMID 35719931, 2022). "In addition, NGFR, a key effector in melanoma invasion and phenotype switching, was among the most upregulated genes after YY1 knockdown." (PMID 35693944, 2022). "There is evidence revealing that YY1 is involved in melanoma resistance to apoptosis." (PMID 35719931, 2022). "It is reported that the function of YY1 has two sides in different cancers; most researches indicate that YY1 is highly expressed in a range of cancer types including breast, gastric, brain, liver, lung, and melanoma." (PMID 35383155, 2022). "To functionally assess whether YY1 alters the melanoma cell migration and invasion potential, we performed siRNA-mediated YY1 knockdown in three human melanoma cell lines and first subjected them to Corning Transwell ® migration assay chambers." (PMID 35693944, 2022). "Exploring the exact role of YY1 on the molecular riddles of the melanoma microenvironment may shed light on new and better treatment strategies against this cancer." (PMID 35719931, 2022). "A deeper characterization of YY1 molecular pathways of action may help to define novel biomarkers useful in melanoma prognosis." (PMID 35719931, 2022). "Together, these findings suggest that YY1 is involved in melanoma invasion and phenotype switching." (PMID 35693944, 2022). "However, still many questions arise regarding the exact role of YY1 in melanoma pathogenesis, progression, and drug resistance." (PMID 35719931, 2022). "Inhibiting YY1 by nitric oxide may also sensitize melanoma cells to immunotherapies, like Fas-L, TRAIL, and anti-PDL1-dependent treatment." (PMID 35719931, 2022). "A deeper characterization of YY1 molecular pathways of action may help define novel biomarkers useful in the prognosis of melanoma." (PMID 35719931, 2022). "Thus, YY1 emerges as a novel regulator of phenotype switching in melanoma, reminiscent of other regulators of NC development that also antagonistically control proliferation vs. invasiveness in melanoma cells." (PMID 35693944, 2022). "Furthermore, the transcription factor YY1 has recently been shown to control comparable metabolic pathways in NC and melanoma cells and to be equally required for both development and melanoma formation." (PMID 34417458, 2021). "Interestingly, both early NC development and melanoma tumorigenesis seem to be particularly sensitive to alterations in the same metabolic processes that are regulated by YY1." (PMID 33102493, 2020). "Through molecular interrogation, we demonstrated that a melanoma-associated intronic variant, rs398206, contributes to allelic expression of MX2 via modifying an enhancer element recruiting the transcription factor, YY1." (PMID 32483191, 2020). "Silencing of YY1 was shown to inhibit proliferation, migration and invasion of melanoma cells." (PMID 31217904, 2019).
melanoma (continued). "Interestingly, while miR-9 was shown to be an inhibitor of melanoma metastasis by downregulating the NF-κB1-Snail pathway, YY1 was shown to suppress miR-9 transcription and hence promote metastatic potential of melanoma cells." (PMID 31824839, 2019). "Thus, this study suggested that the YY1‐miR‐9‐RYBP axis plays a vital role in melanoma tumorigenesis." (PMID 29383875, 2018). "The up-regulation of YY1 protein in melanoma tissues was also validated in selected samples." (PMID 26104682, 2015). "Quantitative RT-PCR analysis was used to determine whether aberrant YY1 and miR-9 expression occurred in melanoma, compared with benign nevi and normal tissue controls." (PMID 26104682, 2015). "Given the fact that, elevated expression or nuclear enrichment of YAP has been observed in multiple types of human cancers, we first assessed the expression level of YY1 mRNA in 14 benign nevi and 24 melanoma specimens, including 15 metastatic melanoma by RT-qPCR analysis." (PMID 26104682, 2015). "We also showed that YY1 could affect RYBP level in melanoma cells, thus forming a YY1 ~ miR-9 ~ RYBP regulatory axis." (PMID 26104682, 2015). "Collectively, our results may identify YY1 as a novel regulator of melanoma that modulates the miR-9 ~ RYBP axis to promote melanoma tumorigenesis." (PMID 26104682, 2015). "Additionally, the YY1 level was observed to be higher, within tumor cells, in metastatic melanomas than in primary melanoma (p < 0.001)." (PMID 26104682, 2015). "Given the regulatory roles of YY1 on miR-9 expression, we continued to detect whether the expression of miR-9 was altered in melanoma patients and cell lines." (PMID 26104682, 2015). "Taken together, these results indicated that RYBP could regulate cell proliferation, migration and invasion of melanoma cells, further confirming the YY1 ~ miR-9 ~ RYBP axis in melanoma cells." (PMID 26104682, 2015). "Because the YY1 was found to be expressed at higher levels in melanoma cell lines WM852, WM1791C, WM8 and WM209, we chose WM1791C and WM209 to perform further assays to test whether YY1 was functionally involved in malignant melanoma tumorigenesis." (PMID 26104682, 2015). "In general, our observations corroborated that YY1 was an oncogenic regulator for human melanoma." (PMID 26104682, 2015). "Hence, regulation of NGFR by YY1-controlled metabolic programs appears to contribute to increased invasiveness and metastasis formation observed upon reduction of YY1 expression levels in melanoma cells." (PMID 35693944, 2022). "Finally, YY1 promotes melanoma angiogenesis, acting as a positive regulator of VEGF." (PMID 35719931, 2022). "Of note, we could not detect a significant difference in tumor growth between YY1 knockdown tumors and control group unlike previously reported after complete YY1 depletion, indicating that the levels of YY1 reduction are relevant for proliferation control of melanoma cells." (PMID 35693944, 2022). "Thus, our findings show that the metabolic regulator YY1 controls phenotype switching in melanoma." (PMID 35693944, 2022). "Interestingly, the YY1-controlled transcriptional program observed in malignant melanoma cells resembled that of a YY1 program active in neural crest (NC) stem cells–the developmental origin of melanocytes and melanoma." (PMID 35693944, 2022). "Therefore, focusing on the detailed biology and administration of therapies that directly target YY1 or crosstalk pathways in malignant melanoma could facilitate the development of new and more effective treatment strategies and improve patients’ outcomes." (PMID 35719931, 2022). "However, it has also been reported that circHIPK3-miR-637-STAT3 could promote oxaliplatin resistance in colorectal cancer through autophagy, and circHIPK3-miR-215-5p-YY1 had the ability to regulate melanoma cell behaviors." (PMID 34776969, 2021).